ALB (albumin)
Diseases named in the same sentence as ALB in open-access papers (continued):
Sharing a sentence is not in itself a finding about the gene and the disease.
ischemia (continued). "The ability of albumin to bind metals is changed in acute ischemia, leading to a metabolically altered protein with decreased metal binding capacity." (PMID 38027791, 2023). "Another theory of the formation of IMA states that due to ischemia (especially myocardial ischemia), fatty acids are released, which bind with albumin, resulting in a decreased affinity for cobalt." (PMID 37685553, 2023). "In a second approach, we used snap-frozen, unfixed tissue of the same mouse model, in which ischemia-affected areas were demarcated by extravasation of intravenously applied FITC-albumin." (PMID 37342767, 2023). "Compared with the non-DME group, the DME group had a higher proportion of insulin use and a higher level of serum ischemia-modified albumin and fasting plasma glucose." (PMID 36203780, 2022). "Recent studies have shown that ischemia-modified albumin (IMA) is not only an indicator of ischemia, but also a marker of oxidative stress." (PMID 35630086, 2022). "Thus, the purposes of this study were to investigate whether the elevated levels of AGE-albumin from activated macrophage cells are implicated in ischemia-induced cardiomyocyte death and to develop therapeutic strategies for AMI based on its underlying molecular mechanisms with respect to AGEs." (PMID 36555270, 2022). "Preclinical studies have illustrated the mechanism of albumin and its effects in models of hemorrhagic shock, endotoxemia, vascular permeability and ischemia." (PMID 36158787, 2022). "It is produced during ischemia or oxidative stress when a series of chemical reactions occur that alter the N-terminus of albumin, thus making it unable to bind to those metals." (PMID 36009309, 2022). "Another marker of oxidative stress that correlates with the severity of the disease expressed by the PASI score is ischemia-modified albumin." (PMID 35204165, 2022). "To evaluate the effect of PEDF34-NP on the ischemia-induced vascular leakage, we measured albumin in the perfused retina." (PMID 36589744, 2022). "The binding site of the amino terminus of albumin changes due to ischemia, reducing its ability to bind metals." (PMID 33623822, 2021). "IMA is an altered type of serum albumin that forms under conditions of oxidative stress, and it increases due to oxidative stress after acute ischemia." (PMID 33356023, 2021). "The three most significant aspects of the extreme gradient boost importance matrix plot were treatment, type of acute aortic dissection, and ischemia-modified albumin levels." (PMID 34604356, 2021). "As with the ranking of the feature importance scores, in both models, the top three features of the mean absolute SHAP values remained as treatment, type of AAD, and ischemia-modified albumin levels." (PMID 34604356, 2021). "After photocoagulation, ischemia caused a breakdown of the BBB, leading to extravasation of Evans Blue bound to albumin to visualize the extent of ischemia." (PMID 34220420, 2021). "The main outcome of the results is that selection of treatment strategies, the type of AAD, and ischemia-modified albumin levels are the most crucial factors to determine in-hospital mortality predictions of AAD." (PMID 34604356, 2021). "Choline and Whole blood choline (WBCHO) were also found in high concentrations after activation of ischemia, alongside the increased circulating levels of free fatty acids and ischemia modified Albumin." (PMID 34805304, 2021). "Our Western blotting analysis showed that in ischemia-injured eyes of control ADAM17flox mice, leakage of albumin was significantly increased compared to sham-operated eyes (~2.5 fold, p < 0.05)." (PMID 32751103, 2020). "According to laboratory findings, hs-CRP and CAR were significantly higher in the ischemia group, while the serum albumin was significantly lower in ischemia group (p<0.05 for each)." (PMID 33094574, 2020). "Recently, a modification of ischemia-dependent human serum albumin (HSA) has been proposed as a serum biological marker of myocardial ischemia." (PMID 32232820, 2020).
ischemia (continued). "Disulfide level, disulfide/native thiol, disulfide/total thiol (P = 0.001) ratios, and ischemia modified albumin levels (ABSU, 0.71 ± 0.08 vs. 0.83 ± 0.07) were found to be higher in autoimmune gastritis patients with delayed gastric emptying (P = 0.001)." (PMID 31814373, 2020). "As a result of exposure to reactive oxygen species in the case of ischemia, the metal (cobalt, copper, zinc) binding capacity of albumin is decreased." (PMID 32482549, 2020). "Nevertheless, there is paucity of data regarding the role of high sensitivity (hs)-C-reactive protein (CRP) to albumin ratio (CAR) in patients with ischemia on gated single photon emission tomography (SPECT) myocardial perfusion imaging (MPI)." (PMID 33094574, 2020). "Serum ischemia-modified albumin values were significantly higher in the patients with telogen effluvium than healthy controls (p < 0.001)." (PMID 32482549, 2020). "In form of an endothelial edema, these alterations precede ischemia-related BBB breakdown for FITC-albumin as early as 30 min after ischemia onset and are therefore likely to promote further loss of the endothelial integrity." (PMID 30744693, 2019). "In contrast, ischemia-affected vessels with apparent FITC-albumin extravasations only showed a discontinuous I-B4 labeling in striatal and cortical areas, or appeared to be partly devoid of any I-B4 binding, at all." (PMID 30744693, 2019). "Ischemia-modified albumin (IMA), calculated through the evaluation of the binding of cobalt to albumin, is a new biomarker for ischemia." (PMID 30762322, 2019). "The plasma concentrations of urea and creatinine and the urinary albumin-to-creatinine ratio were all greater in rats after ischemia than after sham ischemia." (PMID 30110566, 2018). "Johnsen score, ischemia modified albumin (IMA), total antioxidant status (TAS), total oxidant status (TOS), and oxidative stress index (OSI) levels were determined." (PMID 28727368, 2017). "DbCM was also associated with higher TG, HDL, aspartate aminotransferase (AST), ischemia modified albumin (IMA), and troponin levels." (PMID 28791311, 2017). "The ABC test indirectly detects Ischemia Modified Albumin (IMA) by measuring the decreased binding capacity of albumin for cobalt and has been carried out by the Food and Drug Administration (FDA) to detect myocardial ischemia." (PMID 28698768, 2017). "Ischemia modified albumin (IMA) is human serum albumin that is less capable of binding cobalt due to ischemia." (PMID 28478489, 2017). "The authors concluded that addition of albumin improves endothelial integrity as well as heart function after 4-h ischemia, owing to protection of the glycocalyx." (PMID 26314293, 2015). "During acute ischemic conditions, the metal binding capacity of albumin for transition metals is reduced to what is commonly known as ischemia modified albumin (IMA)." (PMID 24564759, 2014). "By limiting the circulation period of FITC-albumin to 60 minutes prior to our observation time points at 5 and 25 hours after ischemia onset, we made sure to precisely capture BBB alterations in this distinct time window." (PMID 23468865, 2013). "Tissue preparation and quantification of BBB integrity in ischemia-affected brain regions using FITC-albumin as permeability marker were described previously." (PMID 22273146, 2012). "Having been the focus of various investigations recently, ischemia-modified albumin (IMA) is helpful in establishing diagnosis in the early stages of ischemia, before necrosis develops." (PMID 22221979, 2012). "We predicted that it binds the transport protein human serum albumin; indeed, this interaction has been validated and found to confer neuroprotection in animal models of ischemia." (PMID 21909252, 2011). "As expected for this model, ischemia predominantly occurred in the proximal section of the middle cerebral artery territory with varying infarct sizes as indicated by FITC-albumin leakage." (PMID 21679435, 2011).
ischemia (continued). "We have previously attributed this increased proton permeability to the measured ischemia-induced increase in free fatty acids within the mitochondria, as the permeability increase is reversed simply by incubating the mitochondria with albumin." (PMID 19671187, 2009). "In contrast, normal microcirculation of lumbar spinal cord was observed after ischemia in rabbits with the depletion of CSF, or replacement of CSF by albumin- or gelatin-modified artificial CSF." (PMID 16174300, 2005). "Treatment strategy, Type of AAD, Ischemia-modified albumin levels." (PMID 41375721, 2025). "Ubiquitous albumin expression may be essential for dolphin peripheral cells, possibly to supply albumin during dive-induced ischemia." (PMID 40296757, 2025). "Theanalysis of Ischemia-Modified Albumin (IMA) occurred through the albumin cobalt-binding test." (PMID 40636198, 2025). "The same study reported that ischemia-modified albumin levels increased more in the on-pump CABG group, suggesting that ischemia may cause an increase in ROS." (PMID 38812632, 2024). "Although there is ongoing uncertainty regarding the exact chemical reactions involved during the biotransformation of native albumin into IMA in the context of an ischemic event, the opposite biotransformation, with the regeneration of albumin, is common following ischemia." (PMID 38888377, 2024). "Co, Cu, and Ni bind to ischemia-modified albumin with a lower affinity than native albumin." (PMID 37887045, 2023). "Recent advances in the understanding of ischemia have shown that it alters the albumin composition." (PMID 37779796, 2023). "Serum albumin is essential for preserving physiological homeostasis as it helps colloid osmotic pressure maintains normal, improves arterial hyporeactivity, decreases ischemia reperfusion harm, and also acts as anti-inflammatory element." (PMID 38027791, 2023). "In addition, in the case of ischemia, an albumin molecule called ischemia-modified albumin (IMA) is formed as a result of structural changes in the last amino terminal that binds metal in the serum albumin structure." (PMID 36253755, 2022). "Furthermore, Food and Drug Administration included Ischemia-Modified Albumin, electrocardiogram and the cardiac Troponin I as ischemia markers for the diagnosis of acute coronary syndromes (ACS), cumulating altogether a 95% sensitivity." (PMID 35783848, 2022). "Serum samples were collected and heart-type fatty acid binding protein (H-FABP), ischemia modified albumin (IMA), interleukin-1β (IL-1β), and interleukin-18 (IL-18) were measured to observe whether Sevoflurane anesthesia had protective effect on myocardium." (PMID 34765646, 2021). "IMA is an albumin that changes its structure as a result of ischemia." (PMID 33984895, 2021). "We have demonstrated in rats that transient ischemia induces a rapid and robust increase in retinal vascular permeability to albumin, with a significant increase as early as 15 min after reperfusion and maintained for at least 2 days, which was the latest time examined." (PMID 34446062, 2021). "The BBB permeability response in our model of histone injection appears to be subtle and size-selective, compared to animal models of Alzheimer’s disease and ischemia, where large molecules like albumin-conjugated Evan’s blue (~ 68 kDa) and IgG (~ 150 kDa) can permeate across the BBB." (PMID 32962721, 2020). "IMA measured by the albumin cobalt binding test is a new biomarker for ischemia." (PMID 30762322, 2019). "The use of prophylactic human albumin (HA) or hypertonic sodium lactate (HSL) prime in mechanical circulatory support during LTx could prevent ischemia–reperfusion (IR) injuries and pulmonary endothelial dysfunction and thus prevent the development of pulmonary graft dysfunction." (PMID 36012201, 2022). "We conducted a systematic review and meta‐analysis of ischemia‐modified albumin (IMA), a marker of oxidative stress, acidosis, and ischemia, in RD patients and healthy controls." (PMID 38888377, 2024).
ischemia (continued). "Recently, another index, i.e., the ratio of two inflammatory markers (CRP to albumin; CAR), was investigated for the prediction of ischemia." (PMID 38398769, 2024). "Ischemia-modified albumin (IMA) has emerged as a potential biomarker of oxidative stress, ischemia, and ED." (PMID 38368495, 2024). "In addition to glycation, albumin, one of the most abundant circulating proteins, can also undergo a series of chemical modifications targeting the N-terminal sequence in the presence of ischemic conditions, which lead to the formation of ischemia-modified albumin (IMA)." (PMID 39224304, 2024). "There is growing evidence that the AGE-RAGE axis plays a major role in the pathogenesis of ischemia reperfusion injury, and this study shows that AGE-albumin induces significant changes in the expression of RAGE in rats with AMI compared to controls." (PMID 36555270, 2022). "An increased fibronectin immunofluorescence signal demarcated ischemia-affected areas in mice, along with an increased collagen IV signal and BBB impairment indicated by serum albumin extravasation." (PMID 33192578, 2020). "To assure, that the described analyses indeed refer to ischemia-affected areas showing BBB breakdown, we applied the established permeability marker FITC-albumin." (PMID 30744693, 2019). "Noteworthy, already 30 min after MCAO, up to 60% of the ischemia-affected vessels showed an endothelial edema, paralleled by edematous astrocytic endfeet, clearly preceding FITC-albumin extravasation." (PMID 30744693, 2019). "The secondary outcome was to compare the measurements of TAS, total oxidant status (TOS), ischemia-modified albumin (IMA) level, and catalase (CAT) level before ischemia onset (t1) and at the t2 and t3 time points." (PMID 31655508, 2019). "In ischemia-affected areas, the vascular Cx43 expression seems to be condensed in vessels showing FITC-albumin extravasation (arrow heads)." (PMID 30744693, 2019). "In areas of FITC-albumin extravasation indicative of BBB breakdown, we observed severe ischemia-related vascular alterations, while contralateral control regions regularly exhibited structurally unaffected vessels." (PMID 30744693, 2019). "The authors perfused an isolated heart (guinea pig) with 5 % albumin, 6 % HES 130/0.4 and saline 0.9 % and observed the fluid extravasation before and after 20 minutes of ischemia." (PMID 26314293, 2015). "Although ischemia-related BBB breakdown is reported to follow a complex and dynamic pattern, detection of FITC-albumin leakage assured investigation of affected areas in a temporally and locally specific manner." (PMID 23468865, 2013). "To investigate the fate of endothelial tight junctions in regions of ischemia-related BBB breakdown, we focused on areas exhibiting fluorescein isothiocyanate (FITC)-labeled albumin (FITC-albumin) extravasation." (PMID 23468865, 2013). "Four or 24 hours after ischemia onset, functional impairment was re-assessed and FITC-albumin administered intravenously obtaining leakage-related blood–brain barrier (BBB) impairment." (PMID 22510241, 2012). "The concomitant changes in expression of metalloproteinases and their endogenous inhibitors have been described in TBI and in ischemia, consistent with the increase in TIMP-1 we observed in response to albumin." (PMID 22507553, 2012). "Four or 24 hours after ischemia onset via eMCAO, 20 mg of FITC-albumin (Sigma, Taufkirchen, Germany; in 1 mL physiological saline solution [NaCl]) was administered intravenously." (PMID 22273146, 2012). "This can explain the low albumin expression levels observed in the brain and heart tissues, as these organs do not experience ischemia and reperfusion and therefore do not strongly rely on the antioxidant ability of albumin." (PMID 40296757, 2025). "Ischemia modified albumin is used in cardiac ischemic diseases to determine the early stages of ischemia in which necrosis has not yet occurred." (PMID 38141595, 2023).
ischemia (continued). "Furthermore, the positive correlations between IMA and fibrinogen, and IMA and FAR are indicative of the role of increased fibrinogen, decreased albumin, and increased FAR in ischemia." (PMID 35881574, 2022). "The long half-life of albumin, together with the rapid normalization of modified albumin levels following ischemia, does not match the description of N-terminal modified IMA." (PMID 28356609, 2017). "Matsuo and colleagues showed that S-0139 administration decreased brain edema and albumin extravasation in a rat ischemia model, where the ischemia was not induced by ET-1 but due to middle cerebral artery filament occlusion." (PMID 21541244, 2011). "Prior to ischemia, rabbits were subjected to the following procedures; 1) CSF depletion, 2) CSF replenishment at 0 mmHg intracranial pressure (ICP), and 3) replacement of CSF with 8% albumin- or 1% gelatin-modified artificial CSF, respectively." (PMID 16174300, 2005). "Thirdly, confounding factors like infection, ischemia, or acute coronary disease, which could impact serum ALB levels, were not taken into account." (PMID 38910183, 2024). "Hypocalcemia may be secondary to hyopalbuminemia (although serum albumin in Ebola-virus infected animals was not significantly related to survival outcome as assessed by logistic regression analysis) and/or renal disease, perhaps due to ischemia." (PMID 25421892, 2014).